MYC (MYC proto-oncogene, bHLH transcription factor)
Diseases named in the same sentence as MYC in open-access papers (continued):
Sharing a sentence is not in itself a finding about the gene and the disease.
cancer (continued). "We showed that ectopic expression of MYC sensitized cells to apoptosis induced by etoposide and camptothecin in cancer cells." (PMID 20111719, 2010). "The MYC gene locus is also known to frequently show copy-number gains or amplifications in various advanced cancers." (PMID 20565940, 2010). "When MYC is over-expressed during cancer development, it can itself induce DNA damage both in a ROS-dependent and ROS-independent manner, thus contributing to genome instability and chromosomal abnormalities." (PMID 20111719, 2010). "Specifically, HIF-1α and the oncogene MYC, which is also a transcription factor, act in concert to "fine tune" cancer cells' adaptive responses to hypoxic environments." (PMID 19948069, 2009). "c-MYC is overexpressed in many cancer types while at the same time, it also exhibits the ability to induce apoptosis." (PMID 20066163, 2009). "MYC is known to be deregulated in a large number of human cancers yet there has been little successful development of drugs that target this important activity." (PMID 19714244, 2009). "Developing therapeutic approaches to inhibit c-MYC would have an enormous impact on the treatment of a wide range of human cancers." (PMID 19134217, 2009). "MYC over-expression in basal cancer in other datasets can be distinguished on the basis of frequency, but our analysis of the five meta-analysis datasets indicates that it is not a prominent feature, ranking below the top 1000 differentially expressed mRNAs." (PMID 19270750, 2009). "Gene amplification at 8q24 and resultant increased expression of MYC is a common occurrence in carcinomas." (PMID 19547694, 2009). "One of these networks that was identified in MG63 cells centers around the c-MYC oncogene and includes genes involved in cellular function and maintenance, small molecule biochemistry, and cancer." (PMID 18698372, 2008). "MYC is not only a proto-typical oncogene when activated in cancers, but it is also a master regulator of normal cell growth, cell proliferation and metabolism." (PMID 18628958, 2008). "An example of a gene network with evidence of potential genetic and epigenetic contribution to the cancer-specific gene expression profile is the c-MYC-related network in MG63 cells." (PMID 18698372, 2008). "Known cancer genes included focal amplifications of MYC (8q24.21), KRAS (12p12.1) and AKT2 (19q13.2), and homozygous deletions of TGFBR2 (3p24.1) and CDKN2A (9p21.3)." (PMID 18535672, 2008). "The MYC proto-oncogenes are essential activators of cell proliferation and have emerged as some of the genes most commonly deregulated in cancer." (PMID 18492263, 2008). "We propose a transcriptional regulatory model perturbed in human cancer with a feedback loop for c-MYC." (PMID 18190704, 2008). "Many of the transcription factors with indirect effects, including PPARG, E2F1, STAT5A, and MYC, have been suggested as targets for cancer therapy." (PMID 18358079, 2008). "The deletions in a region coding let-7c would be the simplest explanation for the reduced level of let-7c in cancer tissues, the miRNA diminishing the activity of c-MYC, therefore contributing to the enhanced proliferation and tumourigenesis." (PMID 17877811, 2007). "The c-MYC transcription factor, on the other hand, is one of the most potent and frequently deregulated oncoproteins in human cancers, therefore its deregulation is regarded as a hallmark of many cancers." (PMID 17877811, 2007). "The c-MYC oncoprotein plays a pivotal role as a regulator of tumorigenesis in numerous human cancers of diverse origin." (PMID 17254356, 2007).
cancer (continued). "We conclude that mechanisms that regulate mitotic division play a critical role in preventing potent oncogenes, such as MYC, from inducing cancer in adult somatic cells." (PMID 15455033, 2004). "c‐MYC (MYC) oncoprotein is dysregulated in the majority of human cancers." (PMID 41537447, 2026). "Similarly, in cancer cells, pharmacologic inhibition or depletion of MYC promotes a diapause-like state marked by reduced proliferation and increased therapy resistance." (PMID 41117706, 2026). "Metabolic alterations in cancer cells are crucially prompted by the oncogenes MYC and KRAS." (PMID 41328353, 2026). "MYC dysregulation occurs in most cancers provoking, profound changes in gene expression." (PMID 41659653, 2026). "MYC is a central transcriptional regulator frequently dysregulated in cancer." (PMID 41537447, 2026). "Consistent with this, cancer diapause-like persister cells exhibit a negative correlation with transcriptional MYC hallmark expression, underscoring MYC’s central and pivotal role in this process." (PMID 41117706, 2026). "MYC is a key driver in many aggressive and therapy-resistant cancers." (PMID 40668928, 2025). "Previous studies have indicated that JAK signaling followed by MYC activation may contribute to the progression of various cancers." (PMID 40124511, 2025). "The MYC levels fluctuated only moderately between cancer cell, iPSC, and MSC lines." (PMID 39621192, 2025). "Furthermore, current research indicates that c-MYC has a role in evading the immune system in cancer." (PMID 40711670, 2025). "Therapeutically, targeting the MYC-p21 axis represents a promising strategy for cancer treatment." (PMID 40076599, 2025). "Based on these data, it is proposed that RG6016 may modulate the HIF-1α pathway via LSD1, UCHL1, and MYC in aggressive cancers such as SCLC, thereby influencing key processes like hypoxia response, metastasis, and neuroendocrine differentiation." (PMID 40428124, 2025). "This nuclear delivery system has the potential to be applied to the MYC targeting to cure cancer." (PMID 40290126, 2025). "For example, in MYC-driven cancers, inhibition of c-MYC may trigger increased MYCN or MYCL expression, maintaining oncogenic signaling pathways." (PMID 40365020, 2025). "MYC is a transcriptional target of β-catenin that regulates the expression of various Gln transporters crucial for the well-known “glutamine addiction” in cancer cells, including SLC38A5." (PMID 40595509, 2025). "In addition to its direct effects on cancer cells, one of the mechanisms by which MYC plays a role in cancer formation is by promoting immune evasion." (PMID 39875774, 2025). "All these data indicated that the pan-cancer function of HuR is primarily centered on cell cycle regulation, while also encompassing metabolism and immune microenvironment modulation mediated by the transcription factors E2F and MYC." (PMID 40853971, 2025). "c-MYC is an important but undruggable oncogene with numerous roles in cancer progression." (PMID 40082888, 2025). "Mapping cancer hallmark BPs distinctly divided the histotypes into two common traits, where HGSC and EC were for example characterized by upregulation of E2F, MYC V1, and MYC V2 targets, whereas MC and CCC showed upregulation of complement." (PMID 40778374, 2025). "Additionally, we explore the potential therapeutic implications of targeting MXD3, given its role in the MYC pathway, which is known to be involved in cancer cell proliferation and survival." (PMID 40406509, 2025). "Indeed, one of the selective GSPT1 degraders, known as MRT-2359 (Monte Rosa), was found to exhibit superior activity against MYC-dependent cancers than against cancers expressing low levels of MYC." (PMID 39875774, 2025). "Furthermore, the upregulation of protein secretion and unfolded protein response pathways aligns with MYC’s known function in driving protein synthesis and processing machinery, as cancer cells must cope with increased protein production demands." (PMID 41273720, 2025).
cancer (continued). "dBET1 induces the degradation of BRD4, suppressing MYC expression and apoptosis in cancer cells." (PMID 39851497, 2025). "Moreover, the strong dependence of circadian on the cell cycle is often altered in many MYC-driven cancers, which still exhibit lineage correlation patterns in cell cycle durations." (PMID 40687789, 2025). "Abnormal activation of c-MYC is one of the most common features of human cancers." (PMID 40698149, 2025). "Metabolism‐related (MP2), cell cycle‐related (MP3) and MYC signalling‐related (MP6) exhibited conserved activation patterns from pre‐malignant to invasive states across all three cancer types, underscoring their roles as core regulatory modules in carcinogenesis." (PMID 40785647, 2025). "However, the study failed to establish a direct m6A-dependent regulatory association between YTHDF1 and c-MYC, thereby leaving room for investigating the divergent regulatory effects of YTHDF1 on c-MYC across different cancers." (PMID 41167308, 2025). "MYC, a well-known eccDNA-amplified driver gene which promotes cancer cell proliferation, immortalization and cross-resistance, was identified in the most cancer types (11 of 12) with the highest EGIS, followed by CCND1 (11 of 12), H3-5 (10 of 12), YWHAZ (10 of 12) and GAPDHS (10 of 12)." (PMID 40478912, 2025). "Targeting the PA2G4–MYC axis represents a promising therapeutic strategy for MYC-driven cancers." (PMID 41002386, 2025). "This indicates that the combination of YY1 and MYC might be the most synergistic in promoting cancer reversion." (PMID 39840939, 2025). "With recent advances in MYC targeting, combining MYC inhibitors with ncRNA therapeutics could provide a powerful new strategy for treating MYC-driven cancers." (PMID 40126351, 2025). "Interestingly, we observed enrichment for cancer-related transcription factors including MYC and JUN family members in all three tissue-specific analyses, as well as in the meta-analysis." (PMID 41282167, 2025). "E2F transcription factors, frequently co-activated with MYC in cancer, have well-established oncogenic roles and may act in parallel to influence splicing regulation." (PMID 41101775, 2025). "Therefore, the MYC/mTOR axis is an attractive therapeutic target in MYC-driven cancers that are addicted to enhanced protein synthesis." (PMID 39779613, 2025). "Although this study provides a pan-cancer map of putative TF regulators, the prognostic and mechanistic relevance of central hubs, particularly MYC, TAF1, and EGR1, requires validation in future studies using independent, cancer type–specific cohorts such as those available from TCGA." (PMID 41155227, 2025). "Targeting MYC and mTOR pathways may offer a more effective therapeutic approach in certain cancer-type, as it addresses multiple drivers for cancer growth and drug resistance." (PMID 39779613, 2025). "Subsequent Gene Set Variation Analysis (GSVA) indicated stronger proliferative activity in these subclusters, with C3/C5 exhibiting higher scores in cancer-related pathways—including E2F targets, G2M checkpoint, and MYC targets V2—compared to other subclusters." (PMID 40895540, 2025). "MYC, an E-box-binding transcription factor, acts as a transcriptional repressor of lysosomal biogenesis by occupying promoters of lysosomal genes and antagonizing TFEB/TFE3 activity; overexpression of MYC suppresses lysosomal and autophagic function in pluripotent stem cells and cancer cells." (PMID 41439996, 2025). "In this context, LACT, through its iron-sequestering activity, and MES, through inhibition of β-catenin signaling and downstream effectors such as CCND1 and MYC, may act synergistically to disrupt cancer-specific vulnerabilities." (PMID 40699726, 2025). "Therefore, while deregulated c-MYC can be a potent driver of cancer growth, its role in induction apoptosis can also be viewed as a protective mechanism for the organism." (PMID 41463190, 2025).
cancer (continued). "Indeed, MYC’s contributions to oncogenesis can be mapped directly onto Hanahan and Weinberg’s “Hallmarks of Cancer”, a conceptual framework that defines the acquired capabilities necessary for malignant transformation." (PMID 41561634, 2025). "Moreover, c-MYC overexpression has been shown to suppress the interferon response through several mechanisms, contributing to resistance to cancer immunotherapy." (PMID 40333779, 2025). "Together, these findings position CoA synthesis as a tractable metabolic node in MYC-high cancers." (PMID 40832336, 2025). "Notably, TERT plays a pivotal role as a transcription (co-)factor, regulating gene expression and modulating key signaling pathways, such as WNT/β-catenin, NF-κB p65, and MYC, which drive cancer onset and progression." (PMID 40227701, 2025). "The mice with MYC knockout exhibit early aging and their age-sensitive abilities decline, but they also live noticeably longer than wild-type mice and have a 3-to-4-fold lower cancer incidence." (PMID 40290126, 2025). "In addition, both FOXC2 and β-catenin hallmark gene sets are correlated with the downregulation of MYC targets, DNA repair, and oxidative phosphorylation, which are known characteristics of cancer progression." (PMID 40227590, 2025). "Therefore, effectively triggering the degradation of both the EZH2 oncoprotein and its MYC partner represents an attractive therapeutic strategy for cancer." (PMID 39823459, 2025). "In addition to being a direct transcriptional target of c-MYC, PD-L1 is also posttranslationally stabilized in cancer." (PMID 39851497, 2025). "MYC plays a central role in metabolic reprogramming by promoting an anabolic state in cancer cells." (PMID 39779613, 2025). "MYC suppresses the expression of uPA and uPAR in cancer cells to stimulate metastasis." (PMID 40290126, 2025). "MYC is one of the most deregulated oncogenic transcription factors in human cancers." (PMID 39779613, 2025). "MYC enables persistent cell proliferation by forcing cancer cells to re-enter the cell cycle." (PMID 40290126, 2025). "The dependency of MYC-driven cancers on CDK4 presents opportunities also for synthetic lethality." (PMID 40076599, 2025). "Moreover, the transcription factor and oncoprotein MYC are potent drivers of many human cancers and can regulate numerous biological activities that contribute to tumorigenesis, and they also play an important role in the development of HCC." (PMID 40171259, 2025). "MYC is a key transcription factor known to contribute to the development of several cancers." (PMID 39510801, 2025). "Another recent study showed that somatic SVs enriched for enhancer hijacking also play a major role in shaping the cancer DNA methylome and regulating the expression of nearby genes, such as MYC, MYCN, TERT, ZFTA, KIAA1549, ATRX, and CDKN2A, in pediatric brain tumors." (PMID 40599851, 2025). "Notably, the Replogle paper focused on mitochondrial genome stress responses, and prior research links MYC to cancer-related phenotypes, such as cell cycle regulation and MYC-dependent apoptosis, through mitochondrial targets." (PMID 40662800, 2025). "Likewise, mTORC1 activity drives the “proliferation, differentiation and long-lived maintenance” of HSC and HSPCs and the MYC proto-oncogene is a critical regulator of cell proliferation and apoptosis and commonly deregulated in cancer." (PMID 39537978, 2025). "The possible reason is that when CCBL2 expression is low, there is aberrant activation of the proto-oncogene MYC in BC cells, and upregulation of the MYC pathway drives cancer; altered glutamine metabolism in MYC-driven BC results in glutamine addiction, which leads to decreased survival." (PMID 41282989, 2025).
cancer (continued). "Overall, this study establishes a clear functional connection between MYC suppression and DDR pathway targeting, offering a concrete example of how direct MYC inhibitors can potentiate existing therapeutic strategies that exploit replication stress and repair dependency in cancer cells." (PMID 41561634, 2025). "We review here the evidence that the MYC/mTOR axis may have attractive druggable targets for cancers addicted to enhanced protein synthesis." (PMID 39779613, 2025). "CDK9 directly regulates MYC gene expression, particularly in cancer contexts." (PMID 40163908, 2025). "This novel mechanism underscores the therapeutic potential of PF-3758309 in targeting RNA polymerase II dysregulation, particularly in transcriptionally addicted cancers like MYC-driven tumors that rely on heightened transcriptional output for sustained proliferation." (PMID 40854914, 2025). "Notably, recent evidence suggests that dysregulation of the MYC/MAX/MXD network contributes to the progression of multiple cancers, highlighting MXD3 as a gene of interest for further investigation in the context of LUSC." (PMID 40406509, 2025). "The proto-oncoprotein c-MYC is another prominent example of a cancer-related TAD." (PMID 40406608, 2025). "MYC, a transcription factor involved in cellular growth and proliferation, is a well-established regulator of pluripotency in healthy contexts and is frequently upregulated in cancer." (PMID 41101775, 2025). "Therefore, we need to be mindful of the possible adverse effects of premature aging and mitochondrial dysfunction, particularly when MYC inhibitors are applied in children's cancers." (PMID 40290126, 2025). "MYC dysregulation plays a crucial role in the tumorigenesis of various cancers, including TNBC." (PMID 40282497, 2025). "Research has revealed that there is a positive feedback circuit between the upregulation of MYC expression, an alteration in glycolysis, and enhanced histone acetylation in Cr(VI)-transformed cells, which promotes Cr(VI)-induced cancer stem cell-like characteristics and carcinogenesis." (PMID 40612865, 2025). "Activated AKT also controls GSK3β, subsequently augmenting MYC activity in cancer cells." (PMID 40027648, 2025). "Given the critical roles of TSPAN8, UCHL1, and MYC in key biological processes in aggressive cancers like SCLC, targeting these molecules may offer valuable therapeutic potential." (PMID 40428124, 2025). "Delmore and colleagues demonstrated that BET inhibitors could disrupt the interaction between bromodomain proteins and acetylated histones, effectively blocking aberrant gene expression in MYC-driven cancers." (PMID 41614813, 2025). "Importantly, the oncogenic potency of MYC stems directly from its hijacking of normal physiological functions, with cancer cells taking over these processes for malignant advantage." (PMID 41561634, 2025). "Specifically, E2F target proteins, MYC targets, and G2/M checkpoint proteins were more abundant, whereas innate immune response proteins reduced upon adaptation to aneuploidy in both model cell lines and malignant tumors." (PMID 39930267, 2025). "We outline many approaches to cancer treatment that target MYC both directly and indirectly." (PMID 40290126, 2025). "Moreover, we show that cancer cells hijack developmental splicing programs, primarily through MYC and potentially other upstream pathways, during carcinogenesis." (PMID 41101775, 2025). "MYC-driven cancers may be particularly sensitive to interruption of cholesterol synthesis since MYC is linked to dysregulation of cholesterol transport and storage." (PMID 40326560, 2025). "MYC dysregulation is estimated to exist in approximately 70% of human cancers." (PMID 40612865, 2025).